IL5 (interleukin 5)
Diseases named in the same sentence as IL5 in open-access papers (continued):
Sharing a sentence is not in itself a finding about the gene and the disease.
Allergy (continued). "The spy-VLP vaccines also effectively broke B cell self-tolerance and induced potent and durable antibody responses upon vaccination with cancer or allergy-associated self-antigens (PD-L1, CTLA-4 and IL-5)." (PMID 27117585, 2016). "Using peripheral blood T-cells, it has been shown that a PI3Kδ selective inhibitor inhibits TCR stimulated IFNγ and IL-17 production from healthy subjects, and IL-5 and IL-13 production from patients with allergy." (PMID 27716212, 2016). "All Th2-related cytokines (IL-4, IL-5, IL-10, and IL-13) were increased by the allergy induction and inhibited by baicalein." (PMID 27561877, 2016). "Prompted by published data that levels of IL-13 are higher in allergic diseases and IL-13 modulates other gene transcription, we exposed B cells from healthy individuals to Th2 cytokines IL-4, or IL-5, or IL-13 in the culture." (PMID 27825134, 2016). "One of the pathological features of allergic diseases is the over-production of T helper (Th) 2 cytokines, including IL-4, IL-5, IL-13, etc., in the sera and the local tissue." (PMID 27825134, 2016). "Collectively, CCR3 is of great value in modulating IL-5-induced chemotaxis, a key step in the allergic reaction, in both BA-E cells and human primary eosinophils." (PMID 27275740, 2016). "Dendritic cells of skin captured allergy to induce the overexpression of Th2 cells to secrete more the levels of IL-4 and IL-5." (PMID 25861366, 2015). "Histamine upregulates Th2 cells proliferation and production of Th2 cytokines, such as IL-4, IL-5, IL-10, and IL-13, and thus drives to development of allergies." (PMID 25960757, 2015). "Th2 cytokines are known to promote the immune response to parasites: IL-4 and IL-13 play a role in the induction of allergy as they stimulate B-cell growth and IgE production, whilst IL-5 typically induces eosinophil differentiation and growth." (PMID 26582546, 2015). "IL5 is directly involved in eosinophil activation and is a key molecule in allergy and eosinophilic inflammation, expressed by CD4+ helper T and B cells, mast cells, and eosinophils." (PMID 26693492, 2015). "In all the subjects there were determined: Total number of eosinophils (Eo), eosinophilic cationic protein (ECP), Interleukin 5 (IL-5) and allergy tests." (PMID 27275299, 2015). "As expected, given the known role of IL-5 in allergy, the mast cells also specifically expressed high levels of the IL-5R." (PMID 25717144, 2015). "Th2 immune response is linked to protection against helminths and bacteria, whereas the regulatory cytokines IL-4 and IL-5 have prominent roles in allergic diseases." (PMID 26588473, 2015). "Increase in production of Th1 cytokines, IL-12 and IFN-γ as well as decrease in Th2 cytokines, IL-4 and IL-5 by LcS contributed to the prevention of seasonal allergy in Japan." (PMID 24936861, 2014). "Two different Th2 subsets have been defined recently on the basis of IL-5 expression – an IL-5+Th2 subset and an IL-5−Th2 subset in the setting of allergy." (PMID 24498448, 2014). "Th2 cells mainly secrete IL-4, IL-5, IL-6 and IL-10, which are involved in humoral immune and allergic reactions." (PMID 24520300, 2014). "The pathological processes of an allergic reaction are thought to be mediated by Th2-type cells which release interleukins such as IL-5 and IL-13." (PMID 24699261, 2014). "Functional relevance of this observation is demonstrated by increased IL-5 and IL-13 production by CD34+ cells and expression of allergy-associated genes by these progenitor cells after interaction with MC-primed BM-MSCs." (PMID 24381572, 2013). "Meanwhile, C44 is more suitable than C48 in the context of allergic diseases, based on its attenuated Th2 (IL-5, IL-6 and IL-10) potential." (PMID 23554802, 2013). "The levels of Th2 cytokines, including IL-4, IL-5, and IL-13, typically increase during an allergic disease." (PMID 23843865, 2013).
Allergy (continued). "Th2 T cells: CD4+ T cells that express T-helper 2 (Th2)-type cytokines, such as interleukin (IL)-4, IL-5 and IL-13, and mediate immune responses in allergic diseases and parasitic infections." (PMID 23828644, 2013). "Th2 cells and their cytokines (IL-4, IL-5 and IL-13) are abundant in allergic disease, and these cytokines play a central role in initiating allergic inflammation." (PMID 24330349, 2013). "We also analyzed the levels of IL-5, an important biomarker of allergic diseases, and detected high levels of IL-5 expression in KD patients during the acute stage of the disease." (PMID 24069052, 2013). "IL-5 levels have been found to be significantly increased in symptomatic subjects with allergic diseases." (PMID 22241467, 2012). "Intermittent allergic rhinitis and bronchial asthma belong to the group of allergic diseases mediated by Th2-type cytokines, such as IL-4, IL-5, IL-13." (PMID 22349136, 2012). "IL-4 and IL5 with helper T-lymphocytes switch from type 1 to type 2, and subsequently high IgE secretion has been proved to be the cardinal pathogenesis of an allergic reaction." (PMID 22899954, 2012). "The release of IL-5 several hours after anti-IgE stimulation has been described as part of the late-phase allergic reaction, related to the influx and activation of eosinophilic granulocytes, for which IL-5 is a key survival and proliferation factor." (PMID 22272213, 2012). "These pathologic processes of allergic reaction are thought to be mediated by Th2-type cells, which preferentially produce IgE-enhancing cytokines such as IL-4 and IL-5." (PMID 22876123, 2012). "It has been reported that p38 MAPK activation can activate transcription factors that result in the expression of IL-4, IL-5, and IL-13 in human T cells in response to antigen exposure in allergic disease." (PMID 21303540, 2011). "It is known that the eosinophil apoptosis inducing effects of glucocorticoids are overridden by survival signals conferred from IL-5, perhaps explaining the high frequency of glucocorticoid resistance seen in allergic diseases." (PMID 21984938, 2011). "Cytokines, such as IL-4 and IL-5, are representative markers of the allergic reaction, based on their roles against allergens." (PMID 21303540, 2011). "In patients with both types of allergy i.e. skin and rhinitis, there was a positive correlation of IL-5 with IL-10 and that of IL-6 with TNF α." (PMID 20616938, 2010). "Type 2 response is related to secretion of IL-4, IL-5, IL-9 and IL-13 which promote induction of IgE and allergic response." (PMID 20184725, 2010). "In fact, a daily low intake in healthy volunteers of 60 ml AndoSanTM for 12 days gave a significant 50% reduction in levels of the allergy-promoting cytokine IL-4 in blood and left the other allergy-related cytokines IL-5, IL-7 and IL-13 at negligible levels." (PMID 19416507, 2009). "GATA-3 plays a critical role in regulating the expression of the cytokines interleukin (IL)-4, IL-5, and IL-13 from T helper-2 (Th2) cells and therefore is a key mediator of allergic diseases." (PMID 19436703, 2009). "Allergic diseases are characterized by the presence of Th2 cells and related cytokines, such as interleukin-4 (IL-4), IL-5, IL-9, and IL-13 with the subsequent development of eosinophils infiltration and chronic inflammation." (PMID 16677403, 2006). "In animal models of allergic disease, it has been established that Th2 responses are mediated by T helper cells that secret cytokines such as IL-4 and IL-5, which induce antibody production in B cells, and IgE plays a central role in allergic responses." (PMID 16504003, 2006). "Eotaxin and IL-5 are representative chemotactic cytokines to studythe activation of skin-homed eosinophils, which in generalrepresent allergic reactions." (PMID 16864900, 2006). "Therefore, the activation of RAS/MAPK pathway induces the production of IL-5 and allergic disease, such as bronchial asthma." (PMID 40514730, 2025).
Allergy (continued). "Specifically, Th2 cells secrete cytokines, such as IL-4, IL-5, and IL-13, which promote IgE production by plasma cells, eosinophil activation, and disruption of mucosal barriers, thereby playing a central role in the pathogenesis of allergic reactions." (PMID 39781535, 2025). "Pre-biologic BEC and FeNO concentrations were elevated in the anti-IL5/5R and anti-IL4Rα biologic groups, whereas patients who subsequently initiated anti-IgE therapy tended to have higher IgE concentrations and one or more allergies." (PMID 38711495, 2024). "It has been demonstrated that T cells in patients with EoG differentiated to IL-4-IL-5+ Th2 cells, while the IL-4+IL-5- subpopulations were dominant in allergic patients, which may explain, at least in part, the different pathophysiology of allergy and EGIDs." (PMID 39136025, 2024). "In addition, IL-4 antagonist has a stronger effect than IL-5 antagonist in alleviating allergy-mediated ETD." (PMID 38274710, 2024). "However, treatment with anti-IL-5 antibodies can be considered as an additional line of treatment in cases of several allergic diseases overlapping, but these studies still need a lot of work and arrangements to define the medical guidelines." (PMID 39062104, 2024). "IL-5 plays a significant role when it comes to allergic diseases mediated by eosinophils." (PMID 39062104, 2024). "IL-4, IL-5 and IL-13 are responsible for the production of non-opsonizing antibodies, allergic reactions, and the suppression of inflammatory reactions caused by Th1 cytokines." (PMID 38787374, 2024). "Indeed, in several studies on allergic diseases, the influx of hyperreactive IL-5–producing Tem2 populations (termed PeTh2) was crucial in driving pathologic eosinophilic inflammation in chronic asthma and in chronic skin disorders." (PMID 38587077, 2024). "Additionally, IL-5 facilitates the migration of eosinophils to tissue sites, typically in the context of allergic reactions." (PMID 39062104, 2024). "For example, arachidonic acid plays a crucial role in allergic diseases, as it generates leukotrienes and prostaglandins, such as prostaglandin E2, which can induce the production of Th2-type cytokines, such as IL-4, IL-5, and IL-13, as well as the synthesis of IgE." (PMID 38378549, 2024). "IL-4 and IL-5 are 2 important Th2 cytokines that are involved in IgE-mediated allergic reactions." (PMID 38274710, 2024). "Also, statistically significant relations for IL5 in infants with allergy and those with FA or ADFA, as well as for IL4 in patients with ADFA or FA+ADFA were observed." (PMID 37520545, 2023). "Moreover, cytokines considered specific to allergy, IL-4, and IL-5 are overexpressed in the ocular surface of DED patients too and another key inflammatory biomarker that can be evidenced in the conjunctiva of DED patients is IL-17 secreted by Th-17 cell." (PMID 37876509, 2023). "It was also shown that methylation profile of IL4, IL5, IL10, IFNG and FOXP3 was associated with environmental exposures and the direction of methylation dynamics differed depending on the presence and types of allergy symptoms." (PMID 37520545, 2023). "IL-5 is mainly produced by T helper-2 (Th2) lymphocytes, mainly involved in the response to parasites and allergies, and group 2 innate lymphoid cells (ILC2), and its expression is regulated by several transcription factors, such as GATA3 (BioCarta GATA3 pathway (p-value = 0.009, FDR = 0.099)." (PMID 36835433, 2023). "With the rapid development of immunology, molecular biology, and biotechnology, many new biological drugs have been designed for the treatment of allergic diseases, including anti-immunoglobulin E (IgE), anti-interleukin (IL)-5, and anti-thymic stromal lymphopoietin (TSLP)/IL-4, to control symptoms." (PMID 36964157, 2023). "In allergies, the local release of IL-5 acts as a chemotactic factor for eosinophils to invade the target organ, as could be the appendices." (PMID 36499410, 2022).
Allergy (continued). "In addition, we observed evidence of intercellular communication via genes implicated in type 2 immunity (CCL11, CCL13, CD5L, IL4, IL5, IL13, IL24) and allergy-linked inflammation (CCL19)." (PMID 35483355, 2022). "Potential targets for developing new therapies for allergic diseases include IgE, TH2 lymphocytes and TH2-derived cytokines, IL-4 and IL-5, and activated mast cells releasing bioactive allergy mediators (histamine, tumor necrosis factor, prostaglandin D2, etc.)." (PMID 35447916, 2022). "An elevation of IL-5 and eosinophil infiltration at target organs is common in allergic reactions." (PMID 36499410, 2022). "Through producing and secreting type 2 cytokines such as IL-4, IL-5 and IL-13, Th2 cells activate B cells to class-switch to IgE and incentive mast cells to release inflammatory mediators, leading to the occurrence of allergic diseases." (PMID 36713372, 2022). "Similarly, CD8+ T lymphocytes, which produce the specific allergens IL-13 and IL-5, have been isolated in high numbers from skin lesions due to allergic reactions." (PMID 36275674, 2022). "Based on these results, it is estimated that although IL-5 may be closely associated with ECP production, its elevated level may not play a crucial role in the development of systemic inflammation in allergic diseases." (PMID 35707392, 2022). "In addition, P. cocos extract significantly decreased interleukin (IL-4 and IL-5) secretion by Type 2 T-helper (Th2) cells immune response, which are related to the allergy response." (PMID 33535602, 2021). "After activation by basophils, ILC2s not only clearly accumulate but also enhance the expression of CCL11, IL-5, IL-9 and IL-13, which further leads to the accumulation of eosinophils and promotes other inflammatory responses in subjects with allergic diseases." (PMID 34177881, 2021). "Interleukin IL-5, IL-4, and IL-13 and innate (ILC-2) lymphoid cells that can maintain and enhance local TH2 inflammation caused by the secretion of TH2 cytokines (IL-13 and IL-5) are the primary cytokines responsible for the allergic response." (PMID 34831860, 2021). "In line with present observations, HDM/DNCB stimulation upregulated the T-bet, STAT3, and GATA3 and other allergy mediating cytokines (IL-4, IL-5, IL-10, IL-13, and IFN-γ) and chemokine (TARC) expression levels, while these were dose-dependently downregulated following SHE treatment." (PMID 32824648, 2020). "Furthermore, allergy immunotherapy inhibited the increasing of IL-25 and Th2 cytokines IL-4, IL-5 and IL-13 with induction of CD4+CD25+ Foxp3+ Treg cells." (PMID 29784924, 2018). "However, PBMCs from allergy patients produce increased levels of Th2-type cytokines including IL-4, IL-5, and IL-13." (PMID 31826046, 2018). "Tissue hypereosinophilia occurs with increased IL-4, IL-5, and IL-13 production in B-cell lymphoma 6 (Bcl6)-knockout (KO) mice, suggesting that Bcl6 participates in allergy pathogenesis and that it may be important for reducing TH2 immune responses." (PMID 29696026, 2018). "These effector-TH2 cells express higher level of IL4, IL5, and IL-9 compared with “classical” TH2 cells and thus could represent pathogenic cells mediating allergy through the IL-33–ST2 signaling pathway." (PMID 29988522, 2018). "This study suggests IL-5 produced in response to parasite infection may mediate a major part of the protection from autoimmunity and allergy by activation of antigen-specific Treg that have been activated by IL-4." (PMID 29163523, 2017). "For instance, in mice with allergen-induced airway hypersensitivity, huang qi injection suppressed the allergic reaction, enhanced interferon-gamma levels (important immune responsive cytokine) and decreased allergen-induced elevations of important allergy related interleukins IL-5 and IL-13." (PMID 29110710, 2017). "In allergic diseases, IL-5 is a key cytokine involved in the induction of eosinophil recruitment." (PMID 28046055, 2017).
Allergy (continued). "As expected, high serum levels of TH2 cytokines IL-5 and IL-13 were observed in the allergy model." (PMID 27445696, 2016). "Chronic rhinosinusitis with nasal polyposis is an inflammatory disease that, although not directly linked to allergy, often displays a Th2-skewed inflammation characterized by elevated local IgE and IL-5 levels." (PMID 27050744, 2016). "In addition to responding to IL-5 producing cells in allergic reaction, eosinophils can express major histocompatibility complex class II and act as antigen presenting cells in allergic airway." (PMID 27275740, 2016). "In this regard, TH2 cell-derived cytokines such as IL-4, IL-5, and IL-13 play a critical role in the pathogenesis of allergic reaction; IL-4 and IL-13 stimulate IgE production, and IL-5 is responsible for eosinophil growth, differentiation, migration, activation, and survival." (PMID 27376063, 2016). "We found positive correlation between Eo and ECP and Eo, ECP and IL-5 with allergy tests." (PMID 27275299, 2015). "There is positive correlation between values of IL-5 and allergy tests." (PMID 27275299, 2015). "The involvement of Th2 cells both helps to explain the joint involvement of IgE-producing B cells (via IL-4 and IL-13), mast cells (via IL-4 and IL-10), and eosinophils (via IL-5) in the allergic inflammatory process and accounts for the other pathophysiologic features of allergies." (PMID 24707309, 2014). "The involvement of Th2 cells both helps to explain the joint involvement of IgE-producing B cells (via IL-4 and IL-13), mast cells (via IL-4 and IL-10) and eosinophils (via IL-5) in the allergic inflammatory process and accounts for the other pathophysiologic features of allergy." (PMID 24624888, 2014). "IL-5 cytokines are the key molecules in allergy and eosinophilic inflammation." (PMID 24764725, 2014). "Therefore, IL-5 has been proposed as a potential molecular target in the treatment of allergic diseases." (PMID 24069052, 2013). "IL-10 is a key regulator of allergic diseases, not only because it downregulates the Th2 cell-derived cytokines IL-4 and IL-5, but also because it directly inhibits the IgE-induced degranulation of mast cells, which leads to a reduced secretion of the inflammatory mediator histamine." (PMID 23346203, 2012). "Our studies show the importance of IL-4 and IL-5 cytokines in response to allergy." (PMID 20616938, 2010). "IgE mediated allergy is promoted by T-helper (Th) 2 lymphocytes producing IL-4, IL-5 and IL-13." (PMID 19900263, 2009). "The development of most immune diseases depends on the cytokines interleukin-2 and interferon-γ produced by type 1 helper T cells (Th1), whereas the development of allergic diseases requires IL-4 and IL-5, both of which are produced by type 2 helper T cells (Th2)." (PMID 15710045, 2005). "The presence of allergic markers, such as elevated immunoglobulin E (IgE) levels and Th-2-driven cytokines (IL-4, IL-5), in the middle-ear effusions of patients with AR, strengthens the hypothesis that allergy-induced inflammation plays a role in OME pathogenesis." (PMID 40497981, 2025). "Furthermore, it is unknown whether a subpopulation of tissue eosinophils that are IL‐5‐independent contributes to the pathobiology of allergic diseases in humans." (PMID 40781582, 2025). "Given the availability of selective anti-IL-5 drugs such as mepolizumab and reslizumab, as well as the IL-5 receptor antagonist benralizumab, it is worth investigating whether they could be used in some cases of allergic disease." (PMID 39062104, 2024). "Therefore, applications of anti-IL-5 treatment could stop or at least slow down most allergic diseases." (PMID 39062104, 2024). "Although cytokine levels, such as IL-5, have traditionally been explored in peripheral samples and in bronchial fluids, there is growing evidence that immune system activation and, specifically, allergy induction impacts neuroimmune function, targeting the hippocampus." (PMID 36831213, 2023).